AXIN1 (axin 1)
Diseases named in the same sentence as AXIN1 in open-access papers (continued):
Sharing a sentence is not in itself a finding about the gene and the disease.
non-small cell lung carcinoma (8 papers, 2019 to 2025). A group of at least three distinct histological types of lung cancer, including non-small cell squamous cell carcinoma, adenocarcinoma, and large cell carcinoma. "It has been shown that RBM47 inhibits EMT and metastasis in non-small cell lung carcinoma by binding to and stabilizing the Axin 1 (AXIN1) mRNA, which suppresses WNT signaling." (PMID 41335176, 2025). "It enhanced the anti-tumor effects of programmed cell death protein 1 (PD-1) inhibitors in serine/threonine kinase 11 (STK11) mutant non-small cell lung cancer (NSCLC) through an axis inhibition protein 1 (AXIN1)-dependent manner." (PMID 39308524, 2024). "MiR-128-3p plays an important role in promoting the metastasis of non-small cell lung cancer (NSCLC) by downregulating the expression of AXIN1, SFRP2, and WIF1." (PMID 38886806, 2024). "Previous evidence has indicated that the reduction of axis inhibition protein 1 (AXIN1) expression is related with the poor differentiation of non-small-cell lung cancer (NSCLC)." (PMID 31143301, 2019). "Moreover, findings indicate that APEX1's influence on AXIN1 transcript splicing in non-small cell lung cancer cells may serve to promote tumor progression." (PMID 38291457, 2024).
endometriosis (7 papers, 2019 to 2023). The growth of functional endometrial tissue in anatomic sites outside the uterine body. "A previous study has described an association between the protein AXIN1 and endometriosis in humans." (PMID 33660232, 2021). "In the enzyme-linked immune-sorbent (ELISA) analysis of AXIN1 from all 172 endometriosis patients, AXIN1 levels were higher in patients than in age-matched controls from the general population (30.0 (17.0–38.0) pg/mL vs. 19.5 (15.0–28.0) pg/mL, p < 0.001)." (PMID 30621017, 2019). "AXIN1, for example, a regulator molecule of the Wnt signaling pathways, has been shown to correlate with disease severity in endometriosis." (PMID 36979692, 2023). "We recently found that AXIN1 is elevated in patients with endometriosis, which is considered an inflammatory disease, and the levels were associated with the degree and duration of gastrointestinal symptoms." (PMID 35565656, 2022). "Before AXIN1 levels can be used as a biomarker for endometriosis to differ between endometriosis and IBS, AXIN1 levels in IBS patients must be determined." (PMID 35565656, 2022). "The cytoplasmic protein AXIN1 is involved in the regulation of apoptosis and has been reported to be a potential new biomarker for endometriosis, with correlations to clinical data such as gastrointestinal symptoms and hormone treatment." (PMID 33660232, 2021). "AXIN1 is a promising protein that should be further investigated as a biomarker for endometriosis diagnosis." (PMID 32143439, 2020). "PCA analysis identified four clusters of proteins, where one cluster differed between endometriosis and controls, with strong correlations for AXIN1 and ST1A1." (PMID 30621017, 2019). "The combination of clinical suspicion of endometriosis in young women and AXIN1 levels in serum/plasma has to be further evaluated in daily practice, to determine its role in clinical practice." (PMID 30621017, 2019). "Plasma AXIN1 levels were analyzed in patients with endometriosis and controls from the general population by ELISA." (PMID 30621017, 2019). "Plasma levels of AXIN1 were elevated in endometriosis compared with age-matched controls from the general population (30.0 (17.0–38.0) pg/mL vs. 19.5 (15.0–28.0) pg/mL, p < 0.001)." (PMID 30621017, 2019). "Currently, the study of diagnostic biomarkers for endometriosis has not yet fully matured, and single markers such as AXIN1, CA-125, and CA-199 have become the focus of research in this area and have shown considerable diagnostic potential." (PMID 38098472, 2023). "The apoptosis-related protein AXIN1 is elevated in endometriosis." (PMID 35565656, 2022). "The results of the current study did not suggest that the localization of the endometriosis lesions is related to an altered profile of gut microbiota, in accordance with a recent study concerning potential plasma biomarkers for endometriosis, such as AXIN1, ST1A1, CXCL9, and OSM." (PMID 33660232, 2021). "Plasma/serum AXIN1 is an interesting biomarker to be further evaluated in endometriosis." (PMID 30621017, 2019). "The increase of AXIN1 in sera/plasma may solely reflect an aberrant activation of the Wnt pathway in endometriosis, and may not reflect causality." (PMID 30621017, 2019). "Serum levels of AXIN1 and ST1A1 were increased in endometriosis compared with MC (p < 0.001) and healthy controls (p = 0.001), whereas CXCL9 levels were decreased." (PMID 30621017, 2019). "AXIN1 was the most interesting protein in the analyses, with a high correlation with factor 2 in the PCA, a factor that separated endometriosis from controls." (PMID 30621017, 2019). "AXIN1 and sulfotransferase 1A1 (ST1A1) were the two most significantly elevated proteins in endometriosis compared to MC and controls." (PMID 30621017, 2019).
endometriosis (continued). "Endometriosis is widely known as an inflammatory condition and serum concentrations of the inflammatory proteins Axis inhibition protein 1 (AXIN1), Sulfotransferase Family 1A Member 1 (ST1A1) and C-X-C Motif Chemokine Ligand 9 (CXCL9) have been found to be altered in women with endometriosis." (PMID 35659226, 2022). "The present finding together with other studies support the hypothesis that AXIN1 may be a potential biomarker to differ between IBS and endometriosis in young women, two groups of patients with gastrointestinal symptoms but normal levels of fecal calprotectin." (PMID 35565656, 2022). "IBS in controls and IBS-like symptoms in patients did not affect AXIN1 levels, which is why the protein could be a potential new biomarker to separate IBS from endometriosis, and thereby reduce the diagnostic delay in endometriosis." (PMID 30621017, 2019). "AXIN1 and ST1A1 had higher values in endometriosis when compared to healthy controls, regardless of the anatomical location of the lesions." (PMID 32143439, 2020). "The current negative correlation between AXIN1 and the long disease duration of IBS must be compared with the shorter disease duration of endometriosis; the low-grade inflammation in IBS may be more apparent in the early stage of the disease and is too low to affect AXN1 levels." (PMID 35565656, 2022). "The proteins AXIN1, ST1A1, CXCL9, and OSM, which showed the greatest differences between endometriosis and controls or symptoms, were not affected by the presence of IBS-like symptoms, localization of endometriosis lesions or hormonal treatment (data not shown)." (PMID 30621017, 2019).
medulloblastoma (6 papers, 2003 to 2025). A malignant, invasive embryonal neoplasm arising from the cerebellum. "CTNNB1 mutations are present in 90% of WNT-activated medulloblastomas; mutations in β-catenin, APC and AXIN1 have also frequently been identified in medulloblastoma." (PMID 35328644, 2022). "ElasticNet coefficients highlighted the predictive importance of genes such as AXIN1, RNF43, STK3, LEF1, and DKK1 for identifying the WNT subtype status in this medulloblastoma validation cohort." (PMID 39851951, 2025).
ovarian carcinoma (5 papers, 2019 to 2023). A malignant neoplasm originating from the surface ovarian epithelium. "Mutations in CTNNB1 (β-catenin) are identified in 16%–54% of endometrioid ovarian cancer patients, and other mutations in APC, AXIN1, and AXIN2, which are key downstream proteins of the Wnt/β-catenin pathway, are also found in different types of ovarian cancer." (PMID 36185280, 2022). "Besides, high frequency mutation of several pathway components have been observed in ovarian cancer, such as CTNNB1, AXIN1/2, and APC." (PMID 36185280, 2022).
osteoporosis (4 papers, 2022 to 2025). A condition of reduced bone mass, with decreased cortical thickness and a decrease in the number and size of the trabeculae of cancellous bone (but normal chemical composition), resulting in increased fracture incidence. "It shows that natural variations in key Wnt pathway genes (LRP5 and AXIN1) directly influence a person’s risk of developing osteoporosis." (PMID 41282593, 2025). "In the genetic study on 1,198 Chinese Han individuals, LRP5 rs11228240 reduced osteoporosis risk, while AXIN1 variants (rs9921222, rs2301522) increased susceptibility, underscoring genetic modulation of Wnt signaling in osteoporosis." (PMID 41282593, 2025). "Data recruited from China’s Second Affiliated Hospital of Xi’an Jiaotong University showed that AXIN1-rs2301522 was significantly associated with the risk of osteoporosis." (PMID 38516378, 2024).
Parkinson disease (4 papers, 2020 to 2024). A progressive degenerative disorder of the central nervous system characterized by loss of dopamine producing neurons in the substantia nigra and the presence of Lewy bodies in the substantia nigra and locus coeruleus. "In addition, a genomic convergence of locus-based GWAS meta-analysis identified AXIN1 is a Parkinson's Disease (PD) gene." (PMID 38291457, 2024). "Additionally, lncRNA NEAT1 impacts Parkinson’s disease pathology by sponging miR-212-3p, which targets AXIN1, while lncRNA SNHG1 exacerbates neuroinflammation in Parkinson’s disease through the miR-7/NLRP3 pathway." (PMID 39280701, 2024). "NEAT1 regulation of the miR-212-3p/AXIN1 pathway might be a therapeutic target for neuroprotection in Parkinson’s Disease." (PMID 36523600, 2022).
sarcoma (4 papers, 2012 to 2023). A usually aggressive malignant neoplasm of the soft tissue or bone. "In order to link Axin1 stabilization, Wnt signaling and anchorage independent growth in sarcoma cells, we started to examine the effect of SEN461 treatment on key components of the canonical Wnt pathway." (PMID 24842792, 2014). "Our findings support the pharmacological stabilization of Axin1 as potential therapeutic treatment for specific subtypes of sarcoma tumors." (PMID 24842792, 2014). "We then asked whether over-expression of Axin1 would affect the phenotypic behaviour of the two sarcoma cell lines examined more in depth." (PMID 24842792, 2014). "In the fibrosarcoma cell line HT-1080, the acute stabilization of the Axin1 protein, sustained by SEN461 treatment, negatively impacts the expression of the proto-oncoprotein c-Myc, an important mediator of sarcoma growth, in vitro and in vivo." (PMID 24842792, 2014). "We also demonstrated that tankyrase inhibitors induce Axin1/2 stabilization in human MDA-MB-231 basal-like cells, human MCF-7 epithelial-like cells and mouse EMT6 sarcoma-like cells, all of which are breast cell lines of diverse origins but with normal APC." (PMID 23144924, 2012). "In sarcoma cells, we found reductions in the protein levels of positive effectors of the Wnt pathway (β-catenin, TCF4, c-MYC and WNT1) and increases in those of negative effectors (GSK3-β and AXIN1) in cells overexpressing EMX proteins." (PMID 34364391, 2021).
basal cell carcinoma (3 papers, 2012 to 2021). A carcinoma involving the basal cells. "Similarly, mmu-miR-329 (targeting Axin1 and Dvl2) is participating in basal cell carcinoma." (PMID 22245972, 2012). "Indeed, the genes driving the basal cell carcinoma pathway are FZD9, FZD7, FZD2, DVL1, and AXIN1, all playing a role in the Wnt signaling pathway, which has already been linked to AD and PD." (PMID 33362460, 2020).
bladder cancer (3 papers, 2019 to 2024). "However, the potential association between AXIN1 and bladder cancer (BC) is unknown." (PMID 31143301, 2019). "Therefore, further studies on larger and more diverse cohorts are needed to validate AXIN1 SNPs as reliable markers to predict the progression and prognosis of bladder cancer." (PMID 31143301, 2019).
cervical cancer (3 papers, 2016 to 2023). A primary or metastatic malignant neoplasm involving the cervix. "The Wnt signaling pathway, which consists of multiple factors (β-catenin, Dvl2, LRP6, Wnt, Naked, C-Myc and Axin1, etc.)involved in cell proliferation, differentiation, migration, and polarity, is associated with many cancers, including cervical cancer." (PMID 35965516, 2022). "Of the top 20 CNA regions >100 kb deletions in cases only, six CNAs occurred on 16p13 that have been reported in cervical cancer, and mutation analysis of the AXIN1 gene located at 16p13 was reported to be involved in the Wnt pathway in cervical carcinomas." (PMID 29083376, 2016). "The tumor suppressor AXIN1, acting as a negative upstream regulator of β-catenin levels and localization, inhibits the expression of Wnt and β-catenin target genes, which represents a potential therapeutic strategy in cervical cancer." (PMID 35965516, 2022).
COVID-19 (3 papers, 2022 to 2024). A disease caused by infection with severe acute respiratory syndrome coronavirus 2. "In male individuals suffering from COVID-19 it was observed that five inflammatory proteins were significantly higher abundant: OPG, AXIN1, CXCL1, CCL11 and CCL10." (PMID 37832397, 2023).
fibromyalgia (3 papers, 2022 to 2025). A chronic disorder of unknown etiology characterized by pain, stiffness, and tenderness in the muscles of neck, shoulders, back, hips, arms, and legs. "Similarly, AXIN1 and SIRT2 are linked to immune regulation and cellular stress and have been linked to the severity of pain, fatigue, and some other symptoms in fibromyalgia." (PMID 39996743, 2025). "The top five proteins that distinguished fibromyalgia patients from plasma controls were in serum STAMBP, SIRT2, CD40, AXIN1 and IL-7 and in CSF (CCL19, CCL23, IL-18, CX3CL1, FGF19, CXCL10, CCL11)." (PMID 36327322, 2022). "Moreover, increased levels of inflammatory serum proteins, including IL-8, IL-37, AXIN1, and SIRT2, have been identified through proteomics and ELISA as correlates of fibromyalgia symptom severity." (PMID 39996743, 2025).
hepatoblastoma (3 papers, 2004 to 2025). Hepatoblastoma (HB) is a malignant hepatic tumor and is the most common pediatric liver cancer. "Conversely, in hepatoblastoma, WNT pathway dysregulation often arises from mutations in CTNNB1 as well as deletions or the epigenetic silencing of AXIN1 and AXIN2, which act as negative regulators of the pathway." (PMID 39851951, 2025). "Mutations in key genes of the WNT pathway, such as CTNNB1 and AXIN1, have been observed in BWS embryonal tumors, including hepatoblastoma, Wilms tumor, and pancreatoblastoma." (PMID 38612397, 2024).
osteosarcoma (3 papers, 2009 to 2024). A usually aggressive malignant bone-forming mesenchymal neoplasm, predominantly affecting adolescents and young adults. "The deletion of Axin 1 and disorder of APC can cause the WNT/β‐catenin signal pathway out of control and cause osteosarcoma development." (PMID 38800967, 2024). "In this study, we demostrate that a recently reported small molecule inhibitor of the canonical Wnt pathway, SEN461, results in Axin1 stabilization followed by decreased total β-catenin levels in the osteosarcoma cell lines." (PMID 24842792, 2014).
pancreatic cancer (3 papers, 2019 to 2023). "MiR-137-mimic significantly promoted AXIN1 and APC, GSK-3β, the phosphorylation of β-catenin on Ser45 expression, and reduced the β-catenin of cytoplasm and nuclear expression in pancreatic cancer cells." (PMID 30866999, 2019).
thyroid cancer (3 papers, 2020 to 2024). "In recent years, in silico analysis suggested that overexpression of the CDH16 gene, whose expression act as a biomarker for thyroid cancer, negatively regulates the AXIN1 expression in thyroid tissue." (PMID 36510340, 2023). "At present, there is only limited information on AXIN1 abnormalities that were mostly reported in poorly differentiated thyroid cancers (e.g. anaplastic form)." (PMID 31758407, 2020). "Therefore, the study of additional cases of malignant struma ovarii, thyroid cancer and cleft palate will help to better understand the relevance of AXIN1 and FOXE1 in thyroid ectopy and malignancy." (PMID 38396644, 2024).
virus infection (3 papers, 2024 to 2025). "Similarly, 83.33% of AXIN1 mutations in our cohort were identified in hepatitis‐infected cases, suggesting a potential link between these mutations and viral infections." (PMID 40344393, 2025). "Upon virus infection, AXIN1 undergoes a phase separation triggered by phosphorylated TANK-binding kinase 1 (TBK1)." (PMID 39384753, 2024).
adenoma (2 papers, 2016 to 2017). A neoplasm arising from the epithelium. "(F) Western blotting for p-Smad2/3, p21, Axin1, β-Catenin, Cyclin D1 in adenomas of WT and miR-31−/− mice resulting from AOM-DSS treatment." (PMID 28870287, 2017).
Anaplastic thyroid cancer (2 papers, 2023 to 2024). "Variants in AXIN1 are found in undifferentiated thyroid tumours." (PMID 38396644, 2024). "Evidence showed the effect of several genetic variants, including catenin (cadherin‐associated protein), beta 1, AXIN1, and APC, and chromosomal abnormalities in the molecular pathogenesis of Anaplastic thyroid cancer." (PMID 36510340, 2023).
asthma (2 papers, 2025). "Further, significant alterations in the maternal inflammation-related proteomic profile from prenatal air pollution were characterized by downregulation of several proteins, including AXIN1, which was also associated with a protective effect on risk of infection and asthma development." (PMID 40595623, 2025). "This study of two prospective birth cohorts demonstrates ambient air pollution alterations in the maternal and child’s proteomic profiles that associates with respiratory infection risk suggesting the AXIN1 protein as a potential target for respiratory infection and asthma prevention in childhood." (PMID 40595623, 2025). "Interestingly, levels of AXIN1 associated with a decreased risk of asthma risk until age 10 years, adjusted odds ratio (aOR): 0.81 (0.66–0.97), p = 0.029 in COPSAC2010." (PMID 40595623, 2025). "This mechanistic link is supported by earlier findings (see Section 5.1), where WTAP-mediated m6A modification of AXIN1 mRNA promotes its YTHDF2-dependent degradation, thereby enhancing Wnt/β-catenin signaling and contributing to airway smooth muscle cell proliferation in asthma." (PMID 41008562, 2025). "Similar to COPSAC2010, AXIN1 levels were associated with a protective effect on risk of respiratory infections, OR (95% CI): 0.50 (0.26–0.98), p = 0.045 and aOR: 0.46 (0.21–1.03), p = 0.059 in the EMIL cohort, which did not have information on asthma status." (PMID 40595623, 2025).
colitis (2 papers, 2022 to 2023). Inflammation of the colon. "Our recent study has demonstrated that deletion of intestinal epithelial Axin1 in epithelial cells and Paneth cells protects the host against colitis by enhancing Akkermansia muciniphila." (PMID 38010886, 2023). "Conditional deletion of Axin1 in epithelial cells and Paneth cells protects against colitis with enriched A. muciniphila in the microbiome community." (PMID 38010886, 2023). "There are four major MIR31 target proteins, Gp130, IL17RA, Axin1, and Lats1/2, with certain probabilities of acting on inflammation and regeneration in colitis." (PMID 36590397, 2022). "Our paper has demonstrated that Axin1 and the microbiome are promising targets for colitis." (PMID 38010886, 2023). "We have demonstrated that PC Axin1 maintains intestinal and microbial homeostasis, which may be the driving factor in protection against colitis." (PMID 38010886, 2023). "It is unknown whether Axin1 plays a similar role in CD11 myeloid cells in the context of colitis." (PMID 38010886, 2023).
diabetes (2 papers, 2016 to 2020). "AXIN1 is down regulated in diabetes condition and CTNNB1 activation is associated with an increment in glucose uptake." (PMID 27490120, 2016).